RNU6-222P (RNA, U6 small nuclear 222, pseudogene)
Gene: Small nuclear RNA gene on chromosome 19 (54,868,939 to 54,869,045, reverse strand). Ensembl gene ENSG00000199308.
Homologues: Orthologues: macaque U6 (93% identical), dog U6 (90% identical), guinea pig U6 (88% identical), guinea pig U6 (85% identical). Paralogues in human: RNU6-11P (93% identical), RNU6-28P (93% identical), RNU6-37P (93% identical), RNU6-29P (93% identical), RNU6-1 (92% identical), RNU6-2 (92% identical), RNU6-39P (92% identical), RNU6-3P (92% identical), RNU6-4P (92% identical), RNU6-5P (92% identical), RNU6-6P (92% identical), RNU6-7 (92% identical), and 1286 more.